JUNB (JunB proto-oncogene, AP-1 transcription factor subunit)
Diseases named in the same sentence as JUNB in open-access papers (continued):
Sharing a sentence is not in itself a finding about the gene and the disease.
cancer (continued). "At the same time, a decrease in JunB expression was shown in the peripheral blood of patients with chronic myelogenous leukemia, which indicates the prospects of considering AP-1 as a marker of the progression of malignant neoplasms." (PMID 34885171, 2021). "As JUNB levels are usually tightly controlled in physiology but often deregulated in cancer, we wondered, whether stromal JUNB may drive malignancy." (PMID 34282521, 2021). "Finally, it has been shown to repress gene expression in epithelial-mesenchymal transition in cancer due to upregulation by TGFβ, demonstrating TGFβ can produce significantly high JunB expression to limit gene transcription." (PMID 30677026, 2019). "JUNB has been also associated to invasion/metastasis in solid tumors including BC and represented as an important target in diseases associated with EMT, including cancer and fibrosis." (PMID 31370904, 2019). "JUNB plays a specific role in cancer cell proliferation, survival and drug resistance." (PMID 30158596, 2018). "Data from cancer studies may support JunB modulation of CXCR4 in other cell types." (PMID 38835488, 2024). "Beyond its role in cancer, overexpression of JUNB may contribute to various inflammatory diseases." (PMID 39409043, 2024). "Consequently, overexpression of ATXN3 dramatically increased JunB protein expression and prolonged JunB half-life, indicating that JunB stabilization by ATXN3 may be involved in PD-L1 upregulation in cancer cells." (PMID 38038129, 2023). "Indeed, we highlighted three pan-cancer NFκB/TNF hallmark genes (EGR1, JUNB, and ZNF36) and identified four candidates (SRGN, CCN2, TNFRSF12A, and ZFP36L1) that are highly potentially involved in NFκB/TNF pathways in various cancers." (PMID 37475016, 2023). "Our results thereby add another facet of JunB to the pathophysiologic functions in MM and underscore worldwide efforts to directly target specific pathognomic AP-1 TFs such as JunB as one of the most promising future strategies in cancer and in MM therapy in particular." (PMID 34007044, 2021). "Since loss of VHL is found in the majority of sporadic RCC and JunB is up-regulated in the VHL-deficient RCC specimens, these results suggest that CCL2 production by cancer cells via aberrant JunB expression might be a predominant mechanism to enhance TAM accumulation in RCC." (PMID 30483271, 2018). "Downregulated genes again were enriched for transcription factors, which included cancer‐related ones such as MYC, JUN and JUNB." (PMID 39508147, 2025). "Several studies credit JUNB or JUND with contradictory roles, even in the same cancer model or disease subtype, and this is a direct result of their participating in AP-1 complexes with a pro-transcription or suppressive activity." (PMID 41020863, 2025). "Meanwhile, the single-cell analysis revealed that the presence of the (CK+/CXCR4+/JUNB-) and (CK+/PD-L1+/CD45) phenotypes were correlated with poorer PFS and OS, respectively, providing interesting biomarkers for this type of cancer." (PMID 38727318, 2024). "This is the case of RhoA/ROCK and JUNB signaling pathways that regulate NFIX expression during myogenesis and are involved in cancer cell proliferation and invasion." (PMID 36901722, 2023).
cancer (continued). "In summary, our study implies that ZIC2 induces M2 TAM polarization, at least in part through regulation of JUNB/MCSF and that ZIC2, JUNB, and CD163 can be utilized as prognostic markers for NPC and as therapeutic targets for cancer immunotherapy." (PMID 37479694, 2023). "JUNB is a transcription factor homologous to JUN, and JUN is specifically expressed in cancer tissues." (PMID 37452081, 2023). "This stable tRNA has a substantially increased efficiency necessary to support a pro‐cancer translation program including c‐Myc, BCL2, RAB31, JUNB and TRAF2." (PMID 37983928, 2023). "c-Jun, c-Fos, NFКB, JunB, EGR-1 and FosB by qRT-PCR after treating PBMCs with cfChPs (10ng) isolated from sera of cancer patients." (PMID 38274821, 2023). "We showed that two members of the IL-6 family, LIF and OSM, induce JunB upregulation in microglia, a finding that was previously reported with respect to LIF-treated human carcinoma cells and to OSM-treated primary chondrocytes." (PMID 37894348, 2023). "JunB mediates the progression of several tumors, including chronic myelogenous leukemia (CML), different lymphomas, and carcinomas." (PMID 37894348, 2023). "In post-treatment tumors, genes such as FOS, JUNB, COL1A2, and DUSP1 have shown to favor cancer proliferation and invasion and were predominantly expressed compared with pre-treatment tumors." (PMID 36505794, 2022). "We further demonstrate that high expression of JUNB both enhances the tumorigenic and metastatic activities of U2OS cancer cells characterized by an epithelial phenotype, when these are xenografted in immunocompromised mice." (PMID 36494864, 2022). "Overexpression of four top candidate genes (CD274 (PD-L1), MCL1, JUNB, and B3GNT2) conferred resistance in diverse cancer cell types and mouse xenografts." (PMID 35338135, 2022). "The transcription factor JUNB plays a crucial role in TMZ resistance, especially in upregulating DNA repair and cancer stemness genes." (PMID 34834399, 2021). "TFF1, IGFBP7, JUNB, CLDN18 and LINC01133 genes were among the top genes of the primary cancer cells." (PMID 34055623, 2021). "Itch, a HECT domain-containing E3 ligase, promotes the ubiquitylation of several proteins (e.g. p70, p63, c-Jun, JunB, Notch, and c-FLIP) and shows a potential target for cancer therapy." (PMID 33643919, 2020). "We find that the three genes that contribute the most to the formation of long feedback loops in the cancer cell line (EGR1, FOSL1, and JUNB) are all involved in the formation of the longest incomplete feedback loops observed in the non-cancer cell line." (PMID 25182846, 2014). "Other members of the Jun family, such as JUNB and JUND, were found to have opposing functions to that of c-JUN, and in most cancers are observed to exhibit decreased expression." (PMID 21711548, 2011). "Using three different cell lines derived from human cancer patients, we confirmed STAT3 binding to the JUNB promoter by chromatin immunoprecipitation." (PMID 19730699, 2009). "Among the DEGs positively modulated in SCE17-exposed cells, we can highlight genes involved in cancer progression, such as FOS, JUN, and JUNB proto-oncogenes, Cyclin Dependent Kinase Inhibitor 1A (CDKN1A), and Tumor Protein 53 Inducible Nuclear Protein 1 (TP53INP1)." (PMID 41440891, 2025). "Importantly, the downregulation of HB-EGF in SCC154 is enough to block the upregulation of JUNB, FOS and FOSB when cancer cells and CAFs are co-cultured." (PMID 39262776, 2024). "The high expression levels of ZIC2 and JUNB were positively correlated and linked to a poor outcomes in NPC patients, implying that ZIC2, JUNB, and CD163 could be utilized as prognostic markers for NPC and as therapeutic targets for cancer immunotherapy." (PMID 37479694, 2023). "Accordingly, the inhibition of JUNB neddylation and protection from degradation by blocking the UBE2M-ITCH interaction could be beneficial for certain cancer treatments." (PMID 37717015, 2023).
cancer (continued). "Actually, an emerging chemotherapy-resistance mechanism, driven by WT1 downregulation, due to transcript cleavage via HTRA2, a protease overexpressed under cytotoxic therapy, has been shown to increase cancer cell survival, based on C-MYC/JUNB upregulation, which is normally repressed by WT1." (PMID 35453662, 2022). "Although cancer-associated fibroblasts drive malignancy as well as invasion and JUNB impacts proliferation in fibroblasts in vitro, we could exclude an altered fibroblast secretome as metastatic driver as fibroblast-specific deletion of JUNB did not influence distant metastasis." (PMID 34282521, 2021). "Therefore, this dynamic expression profile could enhance the role of JUNB and CXCR4 in invasion, establishment of cancer cells in a new tissue and metastasis, confirming related studies." (PMID 36612166, 2022). "As a potent regulator of immune processes, the role of JunB in the TME should not be ignored, which will benefit the development of cancer immunotherapy targets." (PMID 37731821, 2023).
infection (31 papers, 2011 to 2025). The state of being infected such as from the introduction of a foreign agent such as serum, vaccine, antigenic substance or organism. "We next sought to determine the effect of the clonal JunB knockout on susceptibility of the modified cells to HIV-1NL4-3 infection." (PMID 38835488, 2024). "After confirmation of CRISPR/Cas9 editing, the polyclonal population of TZM-GFP JunB KO cells was used to determine susceptibility to HIV-1NL4-3 infection." (PMID 38835488, 2024). "Interestingly, the JunB KO 1–6 cells appeared to have increased susceptibility to infection with VSV-G-pseudotyped and R5-tropic envelope-pseudotyped viruses." (PMID 38835488, 2024). "Moreover, JUNB deficiency in N. brasiliensis compromises type 2 activation during infection, leading to lowered cytokine production and eosinophil recruitment and increased parasite burden." (PMID 36883013, 2023). "As we observed a decrease in syncytia formation in both the polyclonal and clonal cell lines, we suspected that CXCR4 expression was responsible for the significantly decreased infection observed in the JunB KO 1–6 cells." (PMID 38835488, 2024). "The phenotype resulted from downregulation of CXCR4, as infection levels were recovered by reintroduction of CXCR4 in JunB KO cells." (PMID 38835488, 2024). "In contrast, the decrease in CXCR4 expression in the clonal JunB KO 1–6 cells was substantial enough to significantly inhibit infection." (PMID 38835488, 2024). "Using primary human cardiomyocytes (PHCMs), our laboratory demonstrated that T. cruzi induced differential expression of fibrogenic genes during the early phase of infection; these genes include JunB, FOS, EGR1, EGR3 and SNAI1." (PMID 33322418, 2020). "We observed that 24 h after infection, 50% of KCs were GFP+ and deficient for c‐Jun and JunB expression, while the other 50% were Tomato+ KCs and maintained the expression of c‐Jun and JunB." (PMID 31556482, 2019). "Previous studies demonstrated that genes encoding transcription factors such as c-jun, junB, EGR1, and EGR2 were amongst the host genes that were the most rapidly upregulated following infection." (PMID 21479245, 2011). "Genes linked to STAT3 during infection were associated with GO terms such as regulation of cell proliferation (CCND1, JUNB), negative regulation of apoptosis (MCL-1, NFKB1), cytokine-mediated signaling pathway (IL10RA, SOCS1), and immune system process (CRK, IRF9)." (PMID 41115066, 2025). "We next sought to determine the importance of JunB in HIV-1NL4-3 infection." (PMID 38835488, 2024). "Further, while transfection of a CXCR4-expressing plasmid increased susceptibility of JunB KO 1–6 cells to X4-tropic infection as compared to the empty vector control, it did not alter the susceptibility of these cells to R5-tropic, or VSV-G pseudotyped virus." (PMID 38835488, 2024). "In summary, this study demonstrated that TLR2 was required for the accumulation of mtROS after C. pneumoniae infection and highlighted the activation of JunB-Fra-1 by mtROS to promote the expression of MMP2 in the infection-induced VSMC migration and atherosclerotic lesion formation." (PMID 35493076, 2022). "Infection with miR-UL22A knockout virus resulted in significantly increased JunB (p = 0.03) and SERPINE (p<0.01) transcript levels compared to WT infected cells but again infection with the ΔmiR-UL22A mutant virus did not restore transcript levels to that observed in mock-infected cells." (PMID 34411201, 2021). "By combining transcriptome analysis and machine learning, we identified four key targets related to VVTT infection in A293 cells: ARC, JUNB, EGR3, and FOS." (PMID 39940969, 2025). "Components of the JNK and p38 MAPK pathway were induced upon early infection, including the c-Jun N-terminal kinase (JNK) gene MAPK10 as well as the transcription factor AP-1 components FOS, JUN and JUNB." (PMID 38427950, 2024).
infection (continued). "Our screen overwhelmingly identified a transcription factor, JunB, that both prevented HIV-induced cell death and decreased HIV-1NL4-3 infection." (PMID 38835488, 2024). "Here, we find that knockout of JunB downmodulates CXCR4 expression in TZM-GFP cells, blocking HIV-1NL4-3 infection of these cells." (PMID 38835488, 2024). "Post-infection, members of the heat shock protein 70 (HSP70) family, specifically HSPA1B, and transcription factors ATF4, DDIT3, and JUNB showed increased expression (p < 0.05)." (PMID 39600797, 2024). "Two DEGs exhibited a time-specific expression pattern in both infection groups: reduction of FADD at 12 hpi and elevation of JunB at 6 hpi." (PMID 35234615, 2022). "Under Ad-vaspin infection, we observed increases in the levels of c-Fos and c-Jun but no changes in Fosl1, Fosl2, FosB, JunB or JunD." (PMID 40025171, 2025). "To analyze JunB expression during CD8+ T cell responses to acute infections, we adoptively transferred naive CD8+ OVA-specific transgenic (OT-I) T cells into congenic recipient mice, followed by infection with L. monocytogenes expressing OVA antigen (LM-OVA)." (PMID 39425978, 2025). "Notably, 12 of these TFs exhibited distinct phosphorylation patterns upon infection, including MED14, SIN3A, BCL6, cJUN, NFATC1, STAT3, RUNX3, GTF2F1, MED1, JUNB, TLE3, and FOSL2." (PMID 40368139, 2025). "Additionally, we identified three critical targets during VVTT infection—ARC, JUNB, and EGR2—and further validated these targets using qPCR." (PMID 39940969, 2025). "Upon the generation of a clonal JunB knockout cell line, we found that HIV-1NL4-3 infection was blocked in the absence of JunB." (PMID 38835488, 2024). "This was supported by the upregulation of the NF-kB inhibitor genes NFKBIA and NFKBIZ, the AP-1 transcription factor complex genes FOS, JUN, FOSB and JUNB as well as other NF-kB target genes such as TNFAIP3, RELB, NR4A2, DUSP1 and CD69 in response to infection." (PMID 37700317, 2023). "Further, after statistical validation, JUNB, ATF3 and EGR2 genes were attained, which may be used as potential biomarkers with Candida species infection." (PMID 35314002, 2022). "We found 2.64-fold, 2.86-fold, and 0.65-fold increases in c-Fos, JunB, and c-Jun AP-1 family proteins, respectively, in primary WT Mφ infected with T. cruzi (versus no infection; P < 0.001)." (PMID 33172999, 2020). "The level of the epigenetic marker at the position of genes WNT10A, JUNB, FOSL2, TNFAIP3, KLF4 and EDN1 was increased, and decreased at the position of genes MYCN and PCSK9, as was demonstrated by using the in vitro HCV-infection systems." (PMID 31216276, 2019). "We analyzed JunB expression in splenic CD4+ T cells from naïve and P. yoelii 17XNL-infected mice, as shown in S6 Fig, P. yoelii 17XNL infection induced a significant increase in JunB expression in splenic CD4+ T cells, but the levels were not significantly different between the two groups." (PMID 30462731, 2018).
immune disorders (2 papers, 2022 to 2023). "Intriguingly, JunB was reported to be upregulated abnormally in Itch-deficient mice, and these mice developed severe immune disorders and constant skin itching." (PMID 37731821, 2023). "Aged HSCs also show induced expression of the other molecules which are generally implicated in the hematopoietic and immune disorders, AP-1, and HSC quiescence regulators such as BTG, JUNB, and NR41A." (PMID 35923847, 2022). "Given its crucial role in differentiation and cytokine-producing of immune cells, JunB may be a potential regulator for immune disorders." (PMID 37731821, 2023).
animal disease (1 paper, 2017). "We demonstrated in vivo roles of FRA1 and JUNB in mice with CIA, an animal disease model for RA." (PMID 29326694, 2017).
cardiovascular diseases (1 paper, 2024). "Recent studies have revealed that JunB plays a critical role in the development of cardiovascular diseases." (PMID 38826134, 2024).
heart diseases (1 paper, 2018). "However, studies of the role of JunB in heart diseases have been limited." (PMID 29703907, 2018).
metabolic disease (1 paper, 2025). A congenital disorder (due to inherited enzyme abnormality) or acquired (due to failure of a metabolically important organ) disorder resulting from an abnormal metabolic process. "Research indicates a direct correlation between JUNB expression levels and metabolic disorders, impacting fat metabolism, insulin sensitivity, and inflammatory reactions." (PMID 40918148, 2025). "Additionally, JUNB exerts a crucial influence in the TGF-beta signaling pathway, impacting cell proliferation and fibrosis, closely associated with the development of metabolic disorders." (PMID 40918148, 2025). "Hence, targeting JUNB in these signaling pathways presents a promising therapeutic strategy for metabolic diseases, aligning with our experimental findings." (PMID 40918148, 2025).
JUNB also shares sentences with these, for which no sentence is quoted: cervical carcinoma (3 papers); sarcoma (3); Arthritis (2); esophageal squamous cell carcinoma (2); glioblastoma (2); oral squamous cell carcinoma (2); Acute hepatitis (1); acute lymphocytic leukemia (1); acute promyelocytic leukemia (1); adult T-cell leukemia/lymphoma (1); allergic asthma (1); co-infection (1); Cognitive impairment (1); Cutaneous T-Cell Lymphomas (1); dermatitis (1); disc degeneration (1); endometrial cancer (1); esophageal tumor (1); fibrosis (1); HTLV infection (1); influenza (1); kidney cancer (1); lymphopenia (1); lymphoproliferative disorders (1); mental retardation (1); muscle atrophy (1); myasthenia gravis (1); myeloproliferative neoplasm (1); neurogenetic diseases (1); Ollier disease (1).
A further 13 diseases each share a sentence with JUNB in 1 paper.